MOG (myelin oligodendrocyte glycoprotein)
Diseases named in the same sentence as MOG in open-access papers (continued):
Sharing a sentence is not in itself a finding about the gene and the disease.
optic neuritis (continued). "In MOG-ab-positive and AQP4-ab-positive children, maintenance therapy was a protective factor for recurrence, but presenting optic neuritis was a predictor of earlier relapse." (PMID 33841310, 2021). "We present a case of isolated sequential bilateral optic neuritis that was seropositive for both NMO and MOG antibodies." (PMID 34249541, 2021). "MOG-specific antibodies play a central role in the pathogenesis of MOGAD that includes ADEM, anti-aquaporin-4-antibody-seronegative NMOSD, myelitis, and optic neuritis." (PMID 33212299, 2021). "In patients with anti-MOG antibodies, the most frequent clinical presentations include acute disseminated acute encephalomyelitis (ADEM) with optic neuritis (ADEM-NO) or relapses of optic neuritis, although in most cases, the course remains monophasic." (PMID 32722601, 2020). "Needless to say, if MOG-antibody-positive cases with optic neuritis alone or myelitis alone and those with ADEM-like presentation are included, the prevalence of MOG-antibody disease is likely to be higher." (PMID 32670177, 2020). "A recent epidemiologic survey in Japan revealed that of 531 cases of optic neuritis (ON), 23% tested positive for either anti-aquaporin-4 (AQP4) or anti-myelin oligodendrocyte glycoprotein (MOG) antibodies." (PMID 33628473, 2020). "Abs to MOG are found in patients with different clinical phenotypes such as childhood ADEM with encephalopathy, isolated optic neuritis, NMOSD, rarely in patients fulfilling the criteria of MS and in cortical encephalitis with epilepsy." (PMID 33256847, 2020). "Bilateral optic nerve lesions occur more commonly in MOG (and AQP4-IgG) optic neuritis than in MS optic neuritis." (PMID 31212763, 2019). "In children MOG-IgG most frequently expresses clinically as ADEM phenotype, whereas optic neuritis, usually with bilateral involvement, predominates in adults." (PMID 31212763, 2019). "Using CBA antibodies targeting MOG have been recently identified in both children and adults with demyelination disorders including acute disseminated encephalomyelitis (ADEM), optic neuritis (ON), transverse myelitis (TM), and AQP4-seronegative NMOSD." (PMID 31212763, 2019). "In a study of 59 patients with relapsing anti-MOG syndromes (33 children and 26 adults) the inaugural symptoms in the pediatric group were ADEM (36%), bilateral optic neuritis (24%), unilateral optic neuritis (15%)." (PMID 31212763, 2019). "Interestingly, MOG‐antibody‐associated optic neuritis was shown to have a strong correlation with optic nerve head swelling (over 50% of reported patients) which was absent in MS‐associated optic neuritis." (PMID 30578556, 2019). "It is currently a matter of debate if retinal damage following optic neuritis is equally severe in AQP4-NMOSD and MOG-EM and to which extent structural retinal alterations occur in NMOSD independently of optic neuritis attacks." (PMID 30405519, 2018). "OCT displays severe damage to the retinal nerve fiber layer and the ganglion cell layer following attacks of optic neuritis in both AQP4 NMOSD and MOG-EM that correlates with visual function and quality of life." (PMID 30405519, 2018). "We demonstrate a rapid and strong auto‐immune response against CASPR1 in the early pre‐clinical phase of two different EAE mouse models (MOG and PLP mouse model of EAE/optic neuritis)." (PMID 30266776, 2018). "Lastly, time will tell whether all CRION cases are MOG-antibody associated optic neuritis or not." (PMID 29064441, 2017). "We report a case of optic neuritis (ON) secondary to autoimmune encephalitis (AE) in a patient with concomitant antibodies to N-methyl-D-aspartate receptor (NMDAR), gamma-aminobutyric acid-B receptor (GABABR), and myelin oligodendrocyte glycoprotein (MOG)." (PMID 39877347, 2025).
optic neuritis (continued). "The dataset GSE226808, encompassing peripheral blood RNA-sequencing samples from patients with aquaporin-4 positive optic neuritis (AQP4-ON), myelin oligodendrocyte glycoprotein (MOG) antibody positive optic neuritis (MOG-ON), and healthy controls, was utilized in this study." (PMID 39238786, 2024). "Whilst mean age of onset is around the beginning of the fourth decade of life, MOG antibodies are not uncommonly associated with first demyelinating events in children, particularly acute demyelinating encephalomyelitis (ADEM) and optic neuritis (ON)." (PMID 38804311, 2024). "NMOSD, associated with AQP4 antibodies, typically presents with more severe optic neuritis and spinal cord involvement but does not involve MOG antibodies." (PMID 38903369, 2024). "Patients with optic neuropathy have three clinically validated and specific autoantibodies, binding to aquaporin 4, myelin oligodendrocyte glycoprotein (MOG), and collapsin response mediator protein 5 (CRMP5), which are considered helpful in diagnosing and classifying optic neuritis." (PMID 37448746, 2023). "On the other hand, sporadic cases of anti-MOG positive optic neuritis after the AZ COVID-19 vaccine had been reported in non-transplant patients." (PMID 37409268, 2023). "ADEM, Optic neuritis, Transverse myelitis, NMOSD, MOG-AD, CRION, Guillian-Barre syndrome." (PMID 37841344, 2023). "Notably, anti-MOG antibodies are detected in various demyelinating diseases, including AQP4-seronegative NMOSD, recurrent optic neuritis, and acute disseminated encephalomyelitis (ADEM)." (PMID 38138980, 2023). "Peripapillary retinal nerve fiber layer and ganglion cell–inner plexiform layer thicknesses in eyes of patients with isolated MOG-IgA and optic neuritis were not different from those of MOG-IgG patients with optic neuritis (eFigure 3 in Supplement 1)." (PMID 37548987, 2023). "The average duration of follow-up of all the patients included in this study was 23.9 months, 25.2 months in patients with MOG-IgG positive optic neuritis, and 23.3 months in patients with MOG-IgG negative optic neuritis." (PMID 35566760, 2022). "The mean plasma LCN2 values were significantly higher in the patients with MOG-IgG positive optic neuritis when compared to controls and patients with MOG-IgG negative optic neuritis." (PMID 35566760, 2022). "Postinfectious MOG antibody-positive LETM without optic neuritis appears to be a rare entity, with only two other documented cases reported in association with influenza A virus and varicella zoster virus." (PMID 35399911, 2022). "Whether this was optic neuritis due to SARS-CoV-2, MOG antibody disease, or the activation of MOG antibody disease by COVID-19 has been a topic of discussion and needs further observations in clinical practice." (PMID 35743449, 2022). "Quantification of plasma LCN2 levels by ELISA in healthy controls (n = 20), patients with MOG-IgG negative optic neuritis (n = 13), and patients with MOG-IgG positive optic neuritis (n = 6)." (PMID 35566760, 2022). "The absence of both autoantibodies (AQ-4 and MOG) combined with the absence of optic neuritis make the diagnosis of NMOSD unlikely." (PMID 34641797, 2021). "Here, we describe a case of a thirty-nine-year-old-female with recurrent bilateral optic neuritis with positive anti-MOG antibody and anti-MOG syndrome which have not previously been reported from Nepal." (PMID 34484845, 2021). "Here, we describe a case of a thirty-nine-year-old-female with recurrent bilateral optic neuritis with positive anti-MOG antibody, and anti-MOG syndrome has not previously been reported from Nepal." (PMID 34484845, 2021). "In other interesting animal studies, T cell receptor (TCR) transgenic mice specific for MOG spontaneously developed isolated optic neuritis without any evidence of EAE." (PMID 33374173, 2020).
optic neuritis (continued). "In a rat model of myelin oligodendrocyte glycoprotein (MOG)-induced optic neuritis (MOG-ON), FTY720 reduced axonal damage, but did not prevent the apoptosis of retinal ganglion cells (RGCs) in the optic nerve." (PMID 32545828, 2020). "Using CBA, a technique that preserve the conformational structure of full-length human MOG, antibodies targeting MOG have been identified in both children and adults with a variety of phenotypes such as ADEM, optic neuritis, transverse myelitis, NMOSD, and brainstem encephalitis." (PMID 31212763, 2019). "Myelin oligodendrocyte glycoprotein antibodies (MOG-ab) have been identified in a range of acquired demyelinating syndromes in the pediatric population, including acute demyelinating encephalomyelitis (ADEM), optic neuritis (ON), and transverse myelitis (TM)." (PMID 31163654, 2019). "Because MOG expression is higher in the optic nerves than in the spinal cord, even suboptimal doses of MOG can induce experimental optic neuritis in the absence of clinically evident paraparesis in EAE." (PMID 31684959, 2019). "MOG-Abs can be detected in NMOSD with AQP4-Ab seronegative, recurrent optic neuritis, transverse myelitis, multiphasic acute disseminated encephalomyelitis, and combined central and peripheral demyelination (CCPD) syndromes; a proportion of these patients will develop a relapsing type of disease." (PMID 31061727, 2019). "He had additional episodes of optic neuritis with negative workup for infection and rheumatologic disorders except for MOG antibody as it was not available at that time." (PMID 31163654, 2019). "MOG-IgG is associated with a wider clinical phenotype, not limited to NMOSD, with the majority of cases presenting with optic neuritis (ON), encephalitis with brain demyelinating lesions, and/or myelitis." (PMID 29670575, 2018). "MOG-IgG was present in 38% of patients with long myelitis and optic neuritis who do not have AQP4 IgG." (PMID 28840314, 2017). "In terms of clinical presentation, half of the MOG-seropositive (2/4) or AQP4-seropositive (16/31) patients and about two thirds (8/13) of the seronegative patients had an initial presentation with uni-/bilateral optic neuritis (ON)." (PMID 25889963, 2015). "We have presented the first report of a patient with MOG-positive LETM at the C2 to conus level without optic neuritis after influenza A infection." (PMID 25434485, 2014). "Notably, optic neuritis predominated in MOGAD, consistent with the recognized predilection of MOG-IgG disease for bilateral optic nerve involvement, while all NMOSD patients exhibited transverse myelitis, compatible with the hallmark of longitudinally extensive transverse myelitis (LETM)." (PMID 40868427, 2025). "Partially similar to our results, a study conducted on 42 Algerian patients with optic neuritis and/or myelitis by Bouzar and colleagues in 201720 revealed that 7.1% (3/42) of their patients were positive for anti-MOG antibodies and negative for anti-AQP4 antibodies." (PMID 39789036, 2025). "There were 3 patients who did not meet MOGAD criteria but had a clinical diagnosis of MOGAD (false negative); they were all MOG-Ab–positive adults with optic neuritis (2 of whom had relapsing inflammatory optic neuropathy), normal brain and spinal cord MRI, and no supporting features." (PMID 38870448, 2024). "Second, our results may not be generalizable for MOG-related optic neuritis groups because our hospital is an adult referral center; therefore, our results may not be applicable in pediatric populations." (PMID 36977296, 2023). "Optic neuritis can occur alone or in conjunction with other COVID-19-induced neurological illnesses, including myelitis, neuromyelitis optica (NMO) spectrum disorders, anti-myelin oligodendrocyte glycoprotein (anti-MOG) antibody disease, and acute disseminated encephalomyelitis (ADEM)." (PMID 37257164, 2023).
optic neuritis (continued). "Using live CBAs expressing conformational MOG it was subsequently demonstrated that a minority of patients with AQP4-IgG seronegative NMOSD were MOG-IgG positive, expanding the clinical phenotype of this antibody beyond ADEM to include optic neuritis and myelitis." (PMID 35669883, 2022). "LETM is often considered to be within the spectrum of NMO spectrum disorder (NMO-SD), which typically presents with bilateral optic neuritis, and has a strong association with aquaporin-4 (AQP4) antibodies (though not required), with MOG seropositivity being less common." (PMID 35399911, 2022). "Myelin oligodendrocyte glycoprotein (MOG) expressed on the oligodendrocyte cell surface and on the outermost cell surface of the myelin sheath may also be present in patients with NMOSD bilateral optic neuritis." (PMID 34484845, 2021). "Therefore, this study aimed to investigate longitudinally intra-retinal layer changes in eyes without new optic neuritis (ON) in MOG-IgG-seropositive patients." (PMID 31345223, 2019). "Among native-MOG Ab+ children, ADEM was the most prevalent phenotype (38%, 53/139), and most exhibited a monophasic course (79%, 42/53), whereas in adults, optic neuritis (ON) was most common (61%, 91/148), and most presented with relapsing unilateral ON (UON) (27%, 25/91)." (PMID 31481127, 2019). "Using state-of-the-art detection methods (cell-based methods), it was shown that anti-MOG antibodies are found in a subgroup of pediatric patients with acute disseminated encephalomyelitis (ADEM), patients with clinical symptoms of NMOSD, and patients with bilateral optic neuritis in particula r." (PMID 31870389, 2019). "In most cases, retinal damage in MOG-abspositive patients occurs in eyes with a previous history of optic neuritis [81▪▪,82] and could thus reflect secondary degeneration, especially as the retina does not contain MOG expressing cells." (PMID 29465432, 2018). "In the six anti-flotillin-1/2-positive patients in whom the antibody was found prospectively and for whom we could evaluate medical records, testing for anti-AQP4 and anti-MOG was initially requested based on clinically assessed NMOSD core characteristics like myelitis and/or optic neuritis." (PMID 28645295, 2017). "In addition, MOG-IgG testing can be considered, including cerebrospinal fluid when negative in the serum as it can potentially diagnose nearly 10 % of MOGADs that are negative in the serum for patients showing optic neuritis with AMN." (PMID 40265085, 2025). "Identification of MOG-Ab at the time of incident ADS, however, does not predict risk of relapse, as the majority of MOG-Ab-positive children with acute disseminated encephalomyelitis (ADEM) or isolated optic neuritis (with normal brain MRI) experience a monophasic disease course." (PMID 30671648, 2019). "In addition to NMOSD, MOG-Ab is also identified in other demyelinating diseases, including some cases of acute disseminated encephalomyelitis (ADEM), multiphasic demyelinating encephalomyelitis, MS, optic neuritis (ON), and longitudinally extensive transverse myelitis." (PMID 30426010, 2018). "Patients with unilateral optic neuritis, the most frequent MOGAD phenotype, can reliably be tested for non-P42 MOG-IgG epitope at onset, regardless of age and sex." (PMID 40547008, 2025). "Compared with MOG-Ab positive and double negative (AQP4-Ab negative and MOG-Ab negative) optic neuritis, patients with AQP4-Ab positive optic neuritis are more likely to have poor visual acuity after acute phase treatment." (PMID 39470886, 2025). "Optic papillitis with ocular pain and retrobulbar type without ocular pain are more common in patients with anti-MOG antibody and AQP4 antibody, respectively, as compared to idiopathic optic neuritis." (PMID 34484845, 2021). "The reported characteristics of CRION (optic neuritis, dependency on steroids, and the absence of AQP4-Ab) are similar to those described in patients with MOG-IgG disease." (PMID 30382857, 2018).
optic neuritis (continued). "Similarly, Jarius and colleagues in 201630 reported that relapses occurred in 93% of anti-MOG positive anti-AQP4 negative NMOSD patients with disease duration ≥ 8 years and that 88% of the relapses were in the form of optic neuritis." (PMID 39789036, 2025). "Although our patient did not present optic neuritis or transverse myelitis, it would be beneficial to consider running tests for anti-MOG-IgG and serum AQP4 antibodies, which are potentially compatible with MOG-IgG-mediated disease or NMOSD." (PMID 40729267, 2024). "Regarding optic neuritis in the V90 group, the only case had no spinal cord lesions neither optic nerve hyperintensities in magnetic resonance imaging and studied antibodies (anti-AQ4 and anti-MOG) were negative." (PMID 39175548, 2024). "Systematic testing of MOG antibodies in people with VZV optic neuritis is likely not commonly completed and the presence of the two in our patient made a definitive diagnosis of either VZV or MOGAD optic neuritis challenging." (PMID 37845760, 2023). "Notably, MOG-IgG antibodies are of great importance in NMOSD: in one study, 40% of individuals presenting with optic neuritis and transverse myelitis who were negative for AQP4-antibodies were found to be positive for MOG-IgG." (PMID 32671002, 2020). "Interestingly, in our patient cohort presenting with MOG-antibody positive LETM, none of the patients had clinically apparent optic neuritis during the first phase of their disease." (PMID 32055995, 2020). "In children, MOG antibodies are predictive not only of non-MS disease with a specificity of 100% but also of a recurrent non-MS disease course with a specificity of 75% including NMOSD, recurrent ON (RON), MDEM, and ADEM followed by optic neuritis (ADEMON)." (PMID 30555462, 2018). "IgG responses to MOG, localized on the outermost surface of myelin within the CNS, are found in up to 40% of children with CNS demyelinating diseases such as ADEM, MS, NMOSD, isolated optic neuritis or transverse myelitis, but not in control subjects and only rarely in adults with these disorders." (PMID 26907324, 2016).